PUDP (pseudouridine 5'-phosphatase)
Description:
Dephosphorylates pseudouridine 5'-phosphate, a potential intermediate in rRNA degradation. Pseudouridine is then excreted intact in urine.
Synonyms: DXF68S1E; FAM16AX; GS1; HDHD1; HDHD1A
Tractability: Small molecule: it has a high-quality binding pocket.
Gene: Protein-coding gene on chromosome X (6,667,865 to 7,148,165, reverse strand). Ensembl gene ENSG00000130021.
Subcellular location (Human Protein Atlas): Nucleoplasm; Cytosol
Pathways (Reactome):
Metabolism: Pyrimidine salvage
Gene Ontology:
Molecular function: protein binding; pseudouridine 5'-phosphatase activity; phosphatase activity
Cellular component: cytosol
Homologues: Orthologues: chimpanzee PUDP (99% identical), macaque PUDP (97% identical), dog PUDP (86% identical), guinea pig PUDP (81% identical), rat Pudp (73% identical), mouse Pudp (71% identical), tropical clawed frog pudp (68% identical), zebrafish pudp (67% identical), rabbit PUDP (58% identical), Drosophila melanogaster Gs1l (50% identical), Caenorhabditis elegans R151.10 (46% identical), Drosophila melanogaster CG31924 (46% identical), and 3 more.
Diseases named in the same sentence as PUDP in open-access papers:
PUDP is named in the same sentence as 20 diseases in open-access papers, as found by Europe PMC text mining. Sharing a sentence is not in itself a finding about the gene and the disease. The quoted sentences say what the papers report.
Intellectual disability (3 papers, 2020 to 2024). "Diseases associated with PUDP genes include ichthyosis, intellectual disability, X-linked and tricuspid valve stenosis." (PMID 37106349, 2023).
X-linked ichthyosis (2 papers, 2020). "In Family 1, the duplicated segment only encompassed the HDHD1/PUDP gene which encodes pseudouridine-5′-phosphatase and is often deleted in X-linked ichthyosis." (PMID 32842633, 2020).
colorectal cancer (1 paper, 2022). A primary or metastatic malignant neoplasm that affects the colon or rectum. "A previous study demonstrated that Pseudouridine 5’-phosphatase (PUDP) may be a novel prognostic biomarker in colorectal cancer." (PMID 35350563, 2022).
hyperlipidemia (1 paper, 2020). "We identified a novel 3,923 kb deletion within the Xp22.31 region (chrX: 5810838–9733877) containing STS, ANOS1, GPR143, NLGN4X, VCX-A, PUDP, and PNPLA4 in patient 1, who presented with KS, XLI, obesity, hyperlipidemia, and strabismus." (PMID 32670353, 2020).
cancer (4 papers, 2016 to 2024). A tumor composed of atypical neoplastic, often pleomorphic cells that invade other tissues. "Pan-cancer expression analyses of PUDP were performed firstly and we found that PUDP was significantly highly expressed in most tumor tissues." (PMID 35350563, 2022). "In a pan-cancer analysis using the Timer2.0 database, we found that PUDP was significantly up-regulated expressed in 11 types of tumors." (PMID 35350563, 2022). "In this study, the expression level of PUDP in pan-cancer was analyzed firstly." (PMID 35350563, 2022). "We found that PUDP showed a strong positive association with B cell, T cells regulatory (Tregs), CD8+ T cell, CD4+ T cell, Myeloid-derived suppressor cell (MDSC), macrophage, neutrophil, dendritic cell and cancer associated fibroblast (CAF)." (PMID 35350563, 2022). "In this study, a pan-cancer analysis of PUDP expression and prognosis was performed firstly using The Cancer Genome Atlas (TCGA) and Genotype-Tissue Expression (GTEx) data and we found that PUDP may be a potential oncogene for HCC." (PMID 35350563, 2022). "We first analyzed the differential expression of PUDP between tumor and adjacent non-tumor tissues in pan-cancer and used different data sources and databases to ensure the reliability of the results that we analyzed." (PMID 35350563, 2022). "However, in the past, we have paid little attention to PUDP and we are still not clear about its function and role in cancer." (PMID 35350563, 2022).
tumor (3 papers, 2009 to 2022). "Then, we used two datasets, GSE39791 and GSE25097, as well as the HPA database, to re-identify the differences of PUDP expression between HCC tissues with adjacent non-tumor tissues at the mRNA and protein levels." (PMID 35350563, 2022). "We then used the Oncomine database to perform differential expression analysis of PUDP in tumor and normal tissues." (PMID 35350563, 2022). "In the end, the most potential upstream tumor suppressor miRNA for PUDP was identified as let-7c-5p after correlation analysis, expression analysis, and survival analysis." (PMID 35350563, 2022). "Mechanistically, we found that PUDP has a strong positive correlation with tumor-promoting immune cells such as Tregs, MDSCs, CAFs." (PMID 35350563, 2022). "Investigations of the correlation between PUDP expression level and tumor patients’ prognosis were explored and the results demonstrated PUDP was significantly negatively correlated with OS in patients with HCC and PAAD." (PMID 35350563, 2022). "In order to investigate the relationship between PUDP and tumor immune microenvironment, we analyzed the correlation between PUDP and common immune cells in HCC." (PMID 35350563, 2022). "The results of the analysis showed that PUDP is differentially expressed in most tumors and adjacent non-tumor tissues, but whether they all have a prognostic value according to the expression level of PUDP remains unknown." (PMID 35350563, 2022). "The findings suggested that PUDP expression is related to the tumor microenvironment in HCC." (PMID 35350563, 2022). "The results demonstrated that PUDP has a significant differential expression on the level of mRNA and protein between HCC tissues and adjacent non-tumor tissues." (PMID 35350563, 2022). "Surprisingly, there is a strong positive correlation between PUDP and Tregs, MDSC, and other immune cells that promote tumor progression." (PMID 35350563, 2022). "We explored the clinical relevance of PUDP expression in HCC and found that the degree of PUDP expression was clinically significantly correlated with patient gender, and its prevalence was seen in primary HCC compared to the recurrent tumor and solid tissue normal." (PMID 35350563, 2022).
cardiovascular disease (1 paper, 2024). "In terms of relating these sex-biased proteins to cardiovascular disease risk, among the proteins shared between both groups, only a limited number have been previously linked to vascular disease in vascular smooth muscle cells, and these (PUDP and LYRM7) were only upregulated in females (6.25%)." (PMID 39796045, 2024).
PUDP also shares sentences with these, for which no sentence is quoted: ichthyosis (2 papers); X-linked intellectual disability (2); bipolar disorder (1); Cognitive impairment (1); cryptorchidism (1); focal epilepsy (1); Obesity (1); sarcopenia (1); schizophrenia (1); Strabismus (1); testicular cancer (1); tricuspid valve stenosis (1); X-linked ocular albinism (1).